MYO5A (myosin VA)
Diseases named in the same sentence as MYO5A in open-access papers (continued):
Sharing a sentence is not in itself a finding about the gene and the disease.
colorectal cancer (3 papers, 2017 to 2023). A primary or metastatic malignant neoplasm that affects the colon or rectum. "MYO5A was raised in metastatic colorectal cancer and lung cancer tissues and promoted migration of colorectal cancer and lung cancer." (PMID 37667251, 2023). "The upregulation of myosin Va by Snail (a zinc finger transcriptional repressor binding to the promoters of cancer metastasis-related genes) promotes cell invasion and metastasis of human colorectal cancer." (PMID 28903372, 2017). "Our results, showing high mRNA and protein expression of myosin Va in testicular/prostate tumor tissue, are in accordance with previous research, which indicated that myosin Va had a high expression level in colorectal cancer and human lung carcinoma epithelial cells." (PMID 28903372, 2017).
Elejalde syndrome (3 papers, 2008 to 2026). "Myosin Va is a motor protein involved in vesicular transport and its absence leads to movement disorders in humans (Griscelli and Elejalde syndromes) and rodents (e.g. dilute lethal phenotype in mice)." (PMID 19057648, 2008). "Human Elejalde syndrome and Griscelli syndrome type 1 as well as the rodent dilute lethal and dilute opisthotonus phenotypes are characterised by hypomelanosis, severe seizures, opisthotonus and premature death and are due to a lack of functional myosin Va." (PMID 19057648, 2008).
haemophagocytic syndrome (3 papers, 2016 to 2024). "GS1 (OMIM #214450) is caused by homozygous mutation in the gene MYO5A, resulting in hypomelanosis, primary neurological impairment without immunological impairment, and haemophagocytic syndrome." (PMID 33808351, 2021).
Hermansky-Pudlak syndrome (3 papers, 2015 to 2017). Hermansky-Pudlak syndrome (HSP) is a multi-system disorder characterized by oculocutaneous albinism, bleeding diathesis and, in some cases, neutropenia, pulmonary fibrosis, or granulomatous colitis. "In addition, there are several syndromic OCA genes which associated with Hermansky-Pudlak syndrome (HPS 1–7), Chediak-Higashi syndrome(LYST), and Griscelli syndrome types 1 (MYO5A) and 2 (RAB27A)." (PMID 25919014, 2015). "OCA can be caused by TYR, TYRP1 or MATP gene mutation; GS may be caused by pathogenic variants in MYO5A, RAB27A or MLPH; at least nine subtypes of hermansky-pudlak syndrome (HPS), HPS2 caused by variants in AP3B1 which most closely resembles CHS." (PMID 28145517, 2017).
Hyperglycemia (3 papers, 2013 to 2018). An increased concentration of glucose in the blood. "Controlling hyperglycemia in the periphery through ethnopharmacologic glucosidase inhibitor obtained from Pouteria has the potential to reverse the loss of myosin Va in central nervous system neurons." (PMID 25705628, 2014). "This indicates that chronic hyperglycemia induces effects in the protein expression of myosins on brain, and the antioxidant balance (endogenous and exogenous) and reactive oxygen species improves myosin-Va protein level." (PMID 24982856, 2013). "However, myosin-5a (Myo5a) dysfunction may be involved in hyperglycemia-induced suppression of the transmitter release." (PMID 29410956, 2018).
cardiomyopathy (2 papers, 2022 to 2024). A disease of the heart muscle or myocardium proper. "Actin residue E334 interacts with a positively charged patch in the cardiomyopathy loop (CM-loop) of the myosin upper 50 kDa domain of NM2C and Myo5A." (PMID 38446501, 2024).
epilepsy (2 papers, 2021 to 2022). A brain disorder characterized by episodes of abnormally increased neuronal discharge resulting in transient episodes of sensory or motor neurological dysfunction, or psychic dysfunction. "A number of prioritized signals of putative pathogenicity were observed that have no reports of association with epilepsy in the literature including SEC24D, PCCA, MYO5A which may be strong candidates for further functional studies." (PMID 36539902, 2022).
glioblastoma (2 papers, 2021 to 2022). The most malignant astrocytic tumor (WHO grade IV). "MYO5A was also found to be increased in glioblastoma and esophageal carcinoma tissues compared to the normal tissues." (PMID 35478939, 2022). "Besides, myosin VA (MYO5A) may play a crucial role of diagnosis and prognosis in glioblastoma multiforme and gastric cancer." (PMID 34488531, 2021).
laryngeal squamous cell carcinoma (2 papers, 2020 to 2022). A squamous cell carcinoma that arises from the larynx. "Importantly, overexpression of serum MYO5A in laryngeal squamous cell carcinoma predicted cervical nodal occult metastasis and poor prognosis." (PMID 32735728, 2020).
lung carcinoma (2 papers, 2017 to 2023). "The upregulation of myosin Va mediated by Snail promotes the invasion of lung carcinoma epithelial cells and their metastasis." (PMID 28903372, 2017). "After knocking-down the expression of myosin Va by RNAi, a decrease of cell migration velocity is clearly observed in lung cancer cells." (PMID 28903372, 2017).
prostate carcinoma (2 papers, 2017 to 2025). A carcinoma that arises from epithelial cells of the prostate gland. "The results showed that myosin Va's mRNA level was significantly higher in prostate cancer tissues than normal tissues." (PMID 28903372, 2017). "In prostate cancer tissues, myosin Va had a higher fluorescence level and showed a dense bulk distribution." (PMID 28903372, 2017). "Immunofluorescence staining was used to assess localization of myosin Va and F-actin in prostate cancer tissues and normal tissues." (PMID 28903372, 2017). "The purpose of this study is to explore the expression and localization of myosin Va in testicular cancer and prostate cancer, and its specific roles in tumor progression including cell division, migration and proliferation." (PMID 28903372, 2017). "Similarly, the myosin Va's mRNA expression was also detected in the tissues from two prostate cancer patients and a non-cancer patient." (PMID 28903372, 2017).
Stroke (2 papers, 2011 to 2017). Sudden impairment of blood flow to a part of the brain due to occlusion or rupture of an artery to the brain. "Thus, the properties of the recovery stroke are critical forthe myosin Va stepping mechanism." (PMID 21532738, 2011).
acral melanomas (1 paper, 2022). "In another cohort of 34 patients with acral melanomas, we found one tumor with an intrachromosomal rearrangement on chromosome 15 targeting the genes TRPM7 and MYO5A." (PMID 35053440, 2022).
atherosclerosis (1 paper, 2014). A disease characterized by the build-up of fatty material and calcium deposition in the arterial wall resulting in partial or complete occlusion of the arterial lumen. "Inhibition of BMP-2-induced myosin Va expression may represent a potential future therapeutic strategy attenuating atherosclerosis." (PMID 24790701, 2014). "We provide additional insight into the pathophysiology of atherosclerosis, and inhibition of BMP-2-induced myosin Va expression may represent a potential therapeutic strategy." (PMID 24790701, 2014).
autonomic peripheral neuropathy (1 paper, 2022). "However, we found reduced Myo5a expression in the detrusor of these mice, pointing to a previously unexplored autonomic peripheral neuropathy." (PMID 35845995, 2022).
catalepsy (1 paper, 2013). A nervous system disorder characterized by diminished responsiveness and consciousness, and rigidity of the body. "In the “Grey60” module, Myo5a, falls within the range of a previously detected QTL for haloperidol induced catalepsy." (PMID 23555609, 2013).
erectile dysfunction (1 paper, 2014). Persistent or recurrent inability to achieve or to maintain an erection during sexual activity. "Thus, the present study suggests that deficiency of the intracellular motor protein, myosin Va, may be involved in the pathogenesis of gastroparesis and erectile dysfunction." (PMID 24516539, 2014). "Thus it is interesting to speculate that myosin Va defects may contribute to the pathogenesis of diabetic gastroparesis and erectile dysfunction." (PMID 24516539, 2014).
gastric tumor (1 paper, 2020). "Using gastric tumor and adjacent normal tissue specimens collected in our hospital, we showed that MYO5A, PLTP, and TPP1 exhibited higher mRNA and protein expression in tumors than in normal tissue." (PMID 32735728, 2020).
Huntington disease (1 paper, 2019). Huntington disease (HD) is a rare neurodegenerative disorder of the central nervous system characterized by unwanted choreatic movements, behavioral and psychiatric disturbances and dementia. "Moreover, MYO5A and SMS are up-regulated in differentiated neurons and the proteins they encode are less abundant in human brains with Huntington’s disease, a progressive neurodegenerative disorder." (PMID 30733278, 2019).
Intellectual disability (1 paper, 2019). "Phenotypic traits further support a correlation between MyoVa and SMS, since patients harboring loss-of-function mutations in SMS or MYO5A genes share some neurological symptoms, including intellectual disability, seizures, and hypotonia." (PMID 30733278, 2019).
migraine (1 paper, 2023). "The resulting subnetwork included 9 genes: migraine-associated genes APOE, LRP1, CARF, CTIF, RNF213, and ECM1; LAMA2, which is associated with vestibular anomalies in mice; and the neurodevelopment-associated genes MYO5A and KLC2." (PMID 37107589, 2023).
multiple myeloma (1 paper, 2020). "The microarray data also pointed to a significant upregulation of two primary MAFB target genes, i.e., RND3 and MYO5A, which were known to be upregulated in multiple myeloma plasma cells." (PMID 32178359, 2020).
neuropathies (1 paper, 2020). "At least TUBGCP6, SYNE1, BPTF, KIDINS220, MYO5A, VPS13B, TBC1D24) are known to contain mutations causing various neuropathies." (PMID 32561887, 2020).
oral squamous cell carcinoma (1 paper, 2020). "Moreover, overexpression of MYO5A is associated with neck lymph nodes metastasis of oral squamous cell carcinoma." (PMID 32735728, 2020).
pituitary tumor (1 paper, 2025). A benign or malignant neoplasm affecting the pituitary gland. "Myosin 5a (MYO5A) emerges as another promising marker, with studies demonstrating its upregulation in invasive pituitary tumors." (PMID 41206839, 2025). "In conclusion, this review highlights the multifactorial nature of pituitary tumor invasion, driven by MMPs, the uPA system, MYO5A, VEGF, and survivin." (PMID 41206839, 2025).
prostate tumor (1 paper, 2017). "We detected myosin Va in testicular and prostate tumor tissues using sqRT-PCR, western blot, and immunofluorescence." (PMID 28903372, 2017). "Combined with the results from testicular and prostate tissues, we found myosin Va displayed a higher expression level in both testicular tumor and prostate tumor than normal tissues." (PMID 28903372, 2017).
Sciatica (1 paper, 2016). Pain in the lower back and hip radiating in the distribution of the sciatic nerve. "In addition, we identified four variants associated with sciatica at the locus 15q21.2 (MYO5A), which was promising but not replicated." (PMID 27764105, 2016).
Seizure (1 paper, 2021). A seizure is an intermittent abnormality of nervous system physiology characterized by a transient occurrence of signs and/or symptoms due to abnormal excessive or synchronous neuronal activity in the brain. "Seizure in GS1 seems to be related directly to the MYO5A mutation." (PMID 33981514, 2021).
testicular tumors (1 paper, 2017). "In conclusion, our experiments clearly demonstrated an overexpression of myosin Va in testicular tumors and its functions during tumorigenesis." (PMID 28903372, 2017). "In interphase cells, myosin Va was mainly distributed in the nuclear region, which was similar to the IF results in testicular tumor tissues." (PMID 28903372, 2017). "Immunofluorescent staining was conducted to localize myosin Va and F-actin in normal testes and testicular tumors." (PMID 28903372, 2017). "Semi-quantitative RT-PCR was used to detect Myosin Va mRNA expression in muscle tissue, normal testis and testicular tumor." (PMID 28903372, 2017). "In our study, the distribution patterns of myosin Va and microfilament in normal testes and testicular tumor were analyzed and compared." (PMID 28903372, 2017). "However, in the testicular tumor tissue, myosin Va and F-actin were diffusely distributed throughout the whole cell (Cancer 1 and 2)." (PMID 28903372, 2017). "Western blot was performed to determine whether myosin Va protein was expressed in normal testis and testicular tumor." (PMID 28903372, 2017). "However, in testicular tumor tissues, although myosin Va and actin are still co-localized, the two protein represent a diffuse distribution throughout the cells." (PMID 28903372, 2017).
cancer (22 papers, 2013 to 2023). A tumor composed of atypical neoplastic, often pleomorphic cells that invade other tissues. "With regard to mutation, the overall mutational spectrum of MYO5A in pan-cancer were performed by cBioportal based on TCGA database." (PMID 38129784, 2023). "In the future we will seek further evidence for the association between myosin Va and cancer cell migration." (PMID 28903372, 2017). "Positive regulation of myosin Va by Snail is also implicated in the migration of metastatic cancer cells." (PMID 27121062, 2016). "Five of these genes, PTEN, TSC2, RPS6KA3, MYCN and Myo5A, form a connected module (module 9) associated with cancer biology." (PMID 24204314, 2013). "Subsequently, it was disclosed that MYO5A was associated with metastasis in a variety of cancers." (PMID 37667251, 2023). "circFNDC3B positively adjusted the MYO5A expression via spongy miR-370-3p/miR-136-5p, hence achieving the cancer-promoting effect on ESCC." (PMID 37667251, 2023). "circFNDC3B regulated the expression of the target gene MYO5A through spongy miR-370-3p/miR-136-5p, thus achieving the cancer-promoting effect on ESCC." (PMID 37667251, 2023). "According to the TCGA pan-cancer Atlas studies, the copy-number alterations, such as gain or amplification of the MYO5A indeed leads to higher expression of this gene when compared with deep or shallow deletion." (PMID 38129784, 2023). "Considering that some genes are implicated in regulating TIL by inflammation-regulation and cytokine secretion, we performed a correlation analysis to investigate the interaction between MYO5A and immunostimulators in pan-cancer using TISIDB." (PMID 38129784, 2023). "For instance, cancer development-related PI3K-Akt signaling, focal adhesion signaling, integrin-ECM pathways, and EMT processes were all enriched in MYO1B/MYO5A/MYO10 associated DEGs." (PMID 35478939, 2022). "Consistent with the oncogenic effects of PART1 in the TNBC cells, PART1 knockdown downregulated MYO5A, ZHX2 and BICC1, which have all been implicated in cancer progression." (PMID 34072264, 2021). "Interestingly, both MYO5A and MYO5B were found to interact with a key tumor suppressor, phosphatase and tensin homolog (PTEN), in neural cells; however, whether PTEN trafficking underlies functions of either MYO5A or MYO5B motors in cancer cells remains unknown." (PMID 33670106, 2021). "For example, MYO5A expression is increased in a number of highly metastatic cancer cell lines and metastatic colorectal cancer tissues, and epigenetic downregulation of MYO5B has been reported to promote proliferation, invasion and migration in gastric cancer." (PMID 32511227, 2020). "MYO5A show elevated expression in metastatic cancer cell lines derived from various tissue types, and is connected to tumor cell migration and metastasis in vitro and in vivo." (PMID 32511227, 2020). "Results demonstrated that myosin Va fluorescence was weaker in siRNA treated cells, contrasting to cancer cells." (PMID 28903372, 2017). "It has been demonstrated experimentally that myosin Va is required for cancer cell metastasis by affecting cell motility." (PMID 27121062, 2016). "Positive regulation of myosin Va by Snail also seems to be integral in the migration of metastatic cancer cells." (PMID 27121062, 2016). "Two other genes included in the associated loci, Myosin VA (MYOVA) gene on chromosome 15 and Neurotrophin tyrosine kinase receptor 2 (NTRK2) on chromosome 9, are both overexpressed in cancer." (PMID 25629528, 2015). "MYO5A was shown to be regulated by snail and contributed to cancer cell migration and invasion." (PMID 35478939, 2022). "On the other hand, MYO5A has been found to partake in the metastasis of cancer, as it was positively correlated with the expression of Snail, which could trigger the epithelial-mesenchymal transition." (PMID 36249755, 2022). "A link between the protein isoform MYO5A and cancer has already been established." (PMID 32511227, 2020).
cancer (continued). "Furthermore, an increasing pool of data indicates that myosin Va is also involved in other cellular cancerogenic functions such as proliferation and migration of cancer cells." (PMID 28903372, 2017). "In normal cells, myosin Va mainly distributes in cytoplasm, but in cancer cells, it diffuses into the nucleus and may exert special functions related to tumorigenesis." (PMID 28903372, 2017). "Myosin Va is activated by Snail to facilitate cancer cell migration." (PMID 27121062, 2016). "To further explore the relationship between MYO5A expression and immune infiltration patterns in HNSC, we utilized the TIMER 2.0 online tool to analyze expression data from pan-cancer samples." (PMID 38129784, 2023). "Consistent with previous reports about the elevated expression in other cancers, MYO1B, MYO5A, and MYO10 levels were increased in HNSCC tissues compared with adjacent normal tissues whereas MYO5C expression was found to be downregulated." (PMID 35478939, 2022). "The reportedly contrasting functional roles of MYO5A and MYO5B in cancer are puzzling, given the high sequence and structural similarity of these motors." (PMID 33670106, 2021). "On the other hand, MYO5A and SLC4A7 were also reported to promote proliferation, invasion, metastasis and apoptosis resistance in many cancers." (PMID 34336638, 2021). "RT–PCR, western blotting, and the CCK8 assay confirmed that MYO5A, PLTP, and TPP1 exhibited higher expression in GC tissue and were involved in promoting GC cancer cell proliferation." (PMID 32735728, 2020). "Notable alterations in human cancer gene orthologs impacted by SVs in single cases include an ARHGEF12 inversion, a BIRC3 inversion, a CLPTM1L-TERT translocation, a DDIT3 inversion, a MYO5A translocation, and a TCF12 inversion." (PMID 30188888, 2018).